CD47 (CD47 molecule)
Diseases named in the same sentence as CD47 in open-access papers (continued):
Sharing a sentence is not in itself a finding about the gene and the disease.
leiomyosarcoma (16 papers, 2015 to 2024). An uncommon, aggressive malignant smooth muscle neoplasm, usually occurring in post-menopausal women. "Combination of doxorubicin with TTI-621 (anti-CD47 antibody) has shown anti-tumor effect in animal models, especially in tumors which express high number of CD47 and macrophages, such as leiomyosarcoma." (PMID 37007160, 2023). "Preclinical studies reveal the potential of anti-CD47 therapy for leiomyosarcoma, and clinical trials employ mostly pexidarinib or trabectedin." (PMID 34440139, 2021). "The expression of CD47 is enhanced along with the development of leiomyosarcoma cells toward metastasis." (PMID 32902664, 2021). "Anti-CD47 antibodies have been shown to be effective in the treatment of metastatic leiomyosarcoma." (PMID 36860925, 2023). "CD47 blockade by the use of anti-CD47 (B6H12) on the tumor cells potentiates the phagocytosis of these cells by macrophages and this blockade diminishes lung metastasis of leiomyosarcoma LMS04 cells by 70 times." (PMID 32902664, 2021). "Despite promising pre-clinical studies with anti-CD47 mAbs promoting the macrophage-mediated phagocytosis towards malignant cells of leiomyosarcoma, clinical trials in human STSs have not yet been carried out." (PMID 34440139, 2021). "It has been reported that 82% of undifferentiated pleomorphic sarcoma, 78% of leiomyosarcoma, and 70% of Ewing’s sarcoma are negative for CD47, whereas high levels of CD47 were found in angiosarcoma (100% of the cells in 75% of the samples)." (PMID 34207243, 2021).
lymph node metastasis (16 papers, 2014 to 2025). "CD47 positivity showed a tendency to associate with histological differentiation (p = 0.032), mucus production (p = 0.040) and lymph node metastasis (p = 0.049)." (PMID 33799989, 2021). "Furthermore, the analysis demonstrated a significant association between CD47 expression and both lymph node metastasis and advanced tumor stage." (PMID 38532108, 2024). "Moreover, CD47 expression strongly associated with the presence of lymph node metastasis: 9/14 (64.3%) patients had lymph node metastases in the CD47 positive group versus 92/245 (37.6%) in the CD47 negative group (Cochran-Armitage test for trends, p=0.01)." (PMID 25230070, 2014). "In univariate analysis, CD47 expression, FIGO stage, preoperative serum CA125, multidisciplinary surgeries, volume of ascites, and lymph-node metastasis were associated with PFS." (PMID 38317230, 2024). "CD47 expression was correlated with lymph node metastasis, clinical stage, and differentiation degree (P < 0.05), suggesting that as the disease progresses, CD47 expression increases." (PMID 39652550, 2024). "CD47 expression correlated with lymph node metastasis, clinical stage, and differentiation (P<0.05) and was identified as an independent risk factor for poor prognosis." (PMID 39652550, 2024). "Univariate analysis showed that age, CD47 expression, clinical stage, histological grade, infiltration, lymph node metastasis, and Ki67 index correlated significantly with prognosis (P < 0.05)." (PMID 35281519, 2022). "Univariate analysis showed that age, CD47 expression, clinical stage, histological grade, infiltration, lymph node metastasis, and Ki67 index correlated significantly with prognosis." (PMID 35281519, 2022). "High tumor CD47 expression (HR = 1.75), lymph node metastasis (HR = 2.26), and peritoneal metastasis (HR = 5.80) were cited as potential independent risk factors." (PMID 33799989, 2021). "The overexpression of CD47 significantly correlated with T classification, clinical staging, lymph node metastasis and distant metastasis." (PMID 27411490, 2016). "Although tumors without clinical signs of metastasis only very rarely express CD47, patients expressing CD47 show a strikingly poor overall-survival as well as a higher incidence of lymph node metastasis." (PMID 25230070, 2014). "Furthermore, increased CD47 expression correlated with clinical staging, lymph node metastasis and distant metastasis." (PMID 27411490, 2016). "Our study also shows for the first time that co-expression of MET and CD47 in luminal-type primary tumors represents an even better independent predictor for reduced overall-survival compared to expression of MET or CD47 alone and that it strongly correlates with lymph node metastasis." (PMID 25230070, 2014). "MET-CD47 co-expression defined a novel independent prognosticator for overall-survival by multivariate analysis (Cox proportional hazards model: HR: 4.1, p<0.002) and CD47 expression alone or in combination with MET was strongly associated with lymph node metastasis." (PMID 25230070, 2014). "In addition, as for CD47 alone, CD4–MET co-expression was strongly associated with lymph node metastasis (Cochran-Armitage test for trends, p=0.04): 5/7 (71.4%) patients had lymph node metastases in the MET-CD47 double positive group versus 51/143 (35.7%) in the CD47-MET double negative group." (PMID 25230070, 2014). "Certain factors, such as age (≥ 60 years old), lymph node metastasis, TNM staging, differentiation type, and tumor recurrence, resulted in an upregulation of CD47 (p < 0.05)." (PMID 40765033, 2025).
lymph node metastasis (continued). "Cox’s regression analysis was performed using surgical stage, lymph-node metastasis, residual lesion size, CD44 expression, CD47 expression and c-met expression as the dependent variables and survival time as the independent variable." (PMID 25658794, 2015). "Higher CD47 expression levels positively and significantly correlated with the T classification, clinical staging, lymph node metastasis and distant metastasis of NSCLC; but not with age, gender, differentiation status or histological subtypes." (PMID 27411490, 2016). "Expression of CD44 and CD47 correlated with patient surgical stage, chemotherapy resistance and prognosis (all p < 0.05), and expression of c-met correlated with chemotherapy resistance and prognosis (all p < 0.05), but did not correlate with lymph node metastasis (all p > 0.05)." (PMID 25658794, 2015). "However, strong CD47 expression was frequently identified in patient groups with non-clear cell RCC subtypes, higher Fuhrman nuclear grades, lymph node metastasis, and advanced stages." (PMID 36291980, 2022).
bladder tumor (15 papers, 2012 to 2024). "Extensive literature supports the assertion that CD47, identified as an innate immune checkpoint, is markedly expressed in human bladder tumors." (PMID 38339238, 2024). "Compared to control bladder tissues from patients with cystitis, CD47 expression is higher in bladder tumor tissues." (PMID 39335665, 2024). "It has been reported that, after intravesical instillation of the complex of QD and CD47 antibodies, this nanoparticle significantly concentrated in bladder tumors." (PMID 36290934, 2022). "About 10 years ago, the group of Weissman showed that bladder tumor-initiating cells, which are prognostically relevant, expressed more CD47 compared with the rest of the tumor." (PMID 33467469, 2021). "Research has shown that CD47 is expressed in all human bladder tumors, most notably in CD44+ cells." (PMID 36937442, 2023). "Through clinical trials, the authors simultaneously identified five bladder tumor-related proteins, including NMP-22, CD47, CK18, CD47, and CK8." (PMID 36421138, 2022).
triple-negative breast carcinoma (15 papers, 2016 to 2026). An invasive breast carcinoma which is negative for expression of estrogen receptor (ER), progesterone receptor (PR), and human epidermal growth factor receptor 2 (HER2). "A recent study showed that high CD47 expression was associated with epithelial–mesenchymal transition and poor prognosis in triple negative breast cancers." (PMID 36598153, 2023). "Before investigation of psCV1-hIgG1 transfection and fusion protein functionality, expression of CD47 was measured by flow cytometry on human lung and triple-negative breast carcinoma cell lines A549 and MDA-MB-231 and their metastatic variants 231/LM2-4 and 231/LM2-4-EGFPLuc, respectively." (PMID 34729396, 2021). "Comparing the present data with our previous study of the effects of the CD47 antibody B6H12 on the same cells indicates that different CD47 antibodies can have divergent effects on CD47 signaling in triple-negative breast cancer cells." (PMID 38495618, 2024). "In another preclinical study on multiple chemotherapeutic agents and multiple triple-negative breast cancer cell lines, chemotherapy induced transcriptional activation of PD-L1, CD47, and CD73 expression." (PMID 36342599, 2022). "Doxorubicin-mediated upregulation of CD47 was also observed in triple negative breast cancer This upregulation of CD47 increases the number of maplirpacept molecules that can bind to the tumor cell, thus increasing its likelihood to be phagocytosed by macrophages." (PMID 40078999, 2025). "Delivery of JQ1 (indirect inhibitor of MYC) and a CD47 siRNA in cationic lipid NPs significantly inhibits the expression of PD-L1 and CD47, significantly improving therapeutic efficacy in a mouse model of triple-negative breast cancer." (PMID 37416764, 2023). "Another study using aptamers that knock down CD47 and MCL1 suggested additive immune-stimulating effects when combined in a mouse triple-negative breast cancer model." (PMID 36768931, 2023).
medulloblastoma (14 papers, 2015 to 2026). A malignant, invasive embryonal neoplasm arising from the cerebellum. "We investigated the clinicopathological and prognostic relevance of the immune checkpoint molecules B7-H3 (CD276) and CD47 in medulloblastoma." (PMID 42196785, 2026). "In both Brazilian and in silico datasets, the WNT subgroup had significantly higher mRNA levels of CD47 compared to the other medulloblastoma molecular subgroups." (PMID 36825029, 2023). "We further assessed the association of CD276, CD47, CD24, and PVR expression profiles by nCounter and patient survival analysis in the 80 medulloblastomas Brazilian cohort." (PMID 36825029, 2023). "Another pattern that was identified in group 3 medulloblastoma cells is the abundance of CD47 on their surface." (PMID 37568705, 2023). "Compared to the normal cerebellum, the expression level of miR-192 in medulloblastoma cells is lower, and studies indicated that miR-192 suppresses the expressions of ITGAV, ITGB1, ITGB3, and CD47 in medulloblastoma." (PMID 35464451, 2022). "The expression of CD47 is improved in metastatic regions of medulloblastoma in comparison to the primary tumor." (PMID 32902664, 2021). "The employment of a humanized anti-CD47 antibody Hu5F9-G4 diminishes the metastasis in the forebrain and the spine originating from medulloblastoma, notably, via augmenting the phagocytosis of macrophages." (PMID 32902664, 2021). "The results show that the anti-CD47 antibody and irradiation greatly enhanced the phagocytosis of medulloblastoma tumor cells." (PMID 33209523, 2020). "Our results indicated that miR-192-mediated CD47 suppression can inhibit leptomeningeal dissemination of medulloblastoma through molecular cross talk with ITGAVB3." (PMID 26506238, 2015). "After miR-192 transfection, there was a significant reduction in ITGAV, ITGB1, ITGB3, and CD47 in all miR-192-transfected medulloblastoma cells in comparison with NC miR-transfected cells (all P values <0.05)." (PMID 26506238, 2015). "In this framework, systemic treatment with Hu5F9-G4, which disrupts the interaction between CD47 and SIRPα, resulted in shrinkage of primary tumors and leptomeningeal metastasis in mouse models with implanted patient-derived group 3 medulloblastoma xenografts and mouse cell lines of this subgroup." (PMID 37568705, 2023). "Indeed, recent preclinical data has excitingly shown that treatments targeting myeloid cell immune checkpoints, such as the CD47-SIRPα axis, are highly effective in mouse models of medulloblastoma and other childhood brain cancers." (PMID 35309309, 2022). "In summary, this study revealed that the loss of miR-192 expression exerts wide ranging effects on cell proliferation and cell anchoring by activating DHFR and by molecular cross talk between ITGAV, ITGB1, ITGB3, and CD47 in the leptomeningeal dissemination of medulloblastoma." (PMID 26506238, 2015). "In childhood medulloblastoma tissue samples with leptomeningeal dissemination, researchers found decreased microRNA 192 (miR-192); when they overexpressed miR-192 in vitro, they found that CD47 was repressed, affecting integrin alpha V activation and cell proliferation." (PMID 35582455, 2020). "Among the 19 immune checkpoint-related genes evaluated by nCounter in the Brazilian series of medulloblastomas, we found increased mRNA counts of CD24, CD276, CD47, and PVR (CD155)." (PMID 36825029, 2023).
endometrial cancer (13 papers, 2018 to 2025). Primary or metastatic malignant neoplasm involving the endometrium (mucous membrane that lines the endometrial cavity). "Our results seem to be at odds with previous investigations reporting an association between CD47 expression and poor clinical-pathological parameters in OC and endometrial cancers." (PMID 39138571, 2024). "Both CD47 expression assays revealed that CD47 was positively associated with endometrial carcinoma development." (PMID 32984001, 2020). "CD47 positive and strongly positive expression rates in the endometrial cancer group were considerably greater than the endometrial hyperplasia group and the normal endometrium group (P < 0.01)." (PMID 35281519, 2022). "It was discovered that the CD47 expression is considerably stronger in endometrial cancer than in normal endometrium." (PMID 35281519, 2022). "Future studies to determine CD47 details on molecular oncogenesis of endometrial carcinoma are warranted." (PMID 35281519, 2022). "PI3K/Akt/mTOR signaling pathway activation via upregulation of CD47 expression enhances cellular viability and migration ability but suppresses endometrial carcinoma cell apoptosis." (PMID 35281519, 2022). "CD47 overexpression activates the PI3K/Akt/mTOR signaling pathway in endometrial carcinoma cell lines to reduce cancer cell apoptosis." (PMID 36016675, 2022). "The up-regulation of CD47 is reported to enhance cell viability, to suppress apoptosis and to inhibit cell cycle arrest in endometrial carcinoma." (PMID 34439361, 2021). "A previous study observed that CD47 suppresses the progression of endometrial cancer cells by enhancing the sensitivity of M2 Polarized Macrophages on tumor cells." (PMID 32984001, 2020). "CD47 was upregulated in endometrial carcinoma tissues compared with normal endometrial tissue, and higher CD47 expression was observed in endometrial carcinoma patients with later pathological stage, compared with the early stage." (PMID 32984001, 2020). "To determine the regulatory effects of CD47 on endometrial carcinoma cell phenotypes, we selected endometrial carcinoma HEC-1A and Ishikawa cells for subsequent assays." (PMID 32984001, 2020). "Flow cytometry assays were carried out to analyze the modulatory effects of CD47 on endometrial carcinoma cell cycle and apoptosis." (PMID 32984001, 2020). "The results showed that up-regulation of CD47 promoted the proliferation of endometrial carcinoma cells, while down-regulation of CD47 suppressed its growth." (PMID 32984001, 2020). "In this present study, we measured expression levels and regulatory effects of CD47 in endometrial carcinoma." (PMID 32984001, 2020). "After transfected cells were established, functional experiments were performed to analyze the modulatory effects of CD47 on endometrial carcinoma cells." (PMID 32984001, 2020). "CD47 upregulation contributes to the activation of PI3K/Akt/mTOR signaling pathway in endometrial carcinoma cells." (PMID 32984001, 2020). "We found that CD47 expression was higher in endometrial carcinoma tissues, compared with the adjacent tissues." (PMID 32984001, 2020). "Upregulation of CD47 promoted progression of endometrial carcinoma by activating PI3K/Akt/mTOR signaling pathway." (PMID 32984001, 2020). "Purposes: To measure expression levels of CD47 during endometrial carcinoma development, and to determine specific modulatory effects." (PMID 32984001, 2020). "We found that CD47 up-regulation increased PI3K, Akt and mTOR expression in endometrial carcinoma cells, suggesting that CD47 exerted oncogenic effects in endometrial carcinoma via up-regulating the PI3K/Akt/mTOR signaling pathway." (PMID 32984001, 2020). "In this study, CD47 overexpression was also found a protective mechanism in endometrial carcinoma development and down-regulation of CD47 inhibited the proliferation and migration of endometrial carcinoma cells." (PMID 32984001, 2020).
endometrial cancer (continued). "In the present study, we explored the relationship between CD47 expression and the development of endometrial carcinoma." (PMID 32984001, 2020). "CD47 overexpression- or knockdown-cell lines of endometrial carcinoma were established by transfection with plasmid or shRNA." (PMID 32984001, 2020). "Subsequently, functional experiments were performed to evaluate the effects of CD47 on endometrial carcinoma." (PMID 32984001, 2020). "In endometrial cancer, CD47 overexpression further promotes immune evasion in tumor cells." (PMID 40396172, 2025). "CD47 down-regulation was a significant suppressive factor of endometrial carcinoma cell viability." (PMID 32984001, 2020). "Nevertheless, studies of CD47 in endometrial carcinoma are limited." (PMID 32984001, 2020). "All these results reconfirmed that CD47 is an important oncogenic factor in endometrial carcinoma." (PMID 32984001, 2020). "Although CD47 has been involved in cancer progression, at the cell level in vitro CD47 was discovered to be a critical part in enhancing cell migration ability, viability, and inhibiting apoptosis in endometrial carcinoma cells via the PI3K_Akt_mTOR Signaling Pathway." (PMID 35281519, 2022). "Blocking CD47 may be an immunotherapeutic pathway for the treatment of endometrial carcinoma." (PMID 32984001, 2020). "However, the expression of CD47 in endometrial cancer (EC) and the role of CD47-SIRPα in the TAMs which mediate the progression of EC remain unclear." (PMID 30525058, 2018). "Therefore, we believe that CD47 may be a viable OMI target for endometrial carcinoma." (PMID 40385528, 2025). "We found that up-regulation of CD47 promoted the proliferation and migration of HEC-1A and Ishikawa endometrial carcinoma cells, and inhibited apoptosis." (PMID 32984001, 2020). "Kaplan–Meier survival analysis demonstrated that endometrial cancer patients with positive CD47 expression had considerably greater mortality than those with no positive CD47 expression (P < 0.01)." (PMID 35281519, 2022). "We classified pathological stages of endometrial cancer patients according to FIGO criteria and found CD47 mRNA expression levels were higher in the stage III-IV groups, further suggesting a correlation between CD47 mRNA expression levels and endometrial carcinoma progression." (PMID 32984001, 2020). "Besides, CD47 down-regulation reduced PI3K, Akt, and mTOR expression in endometrial carcinoma cells further confirmed this." (PMID 32984001, 2020). "The strongly positive expression of CD47 could be observed in endometrial cancer, but none was observed in normal endometrium." (PMID 35281519, 2022). "We also detected a negative correlation between CD47 expression and the ratio of S and G2/M stage cells in HEC-1A and Ishikawa cells, suggesting that up-regulation of CD47 inhibited apoptosis in endometrial carcinoma cells by modulating the cell cycle." (PMID 32984001, 2020).